KMT2D (lysine methyltransferase 2D)
Diseases named in the same sentence as KMT2D in open-access papers (continued):
Sharing a sentence is not in itself a finding about the gene and the disease.
lung carcinoma (23 papers, 2018 to 2026). "It has been reported that KMT2D loss directly decreases the expression of PER2 or IGFBP5 in lung cancer and melanoma respectively, which leads to the subsequent increased glycolysis." (PMID 39117659, 2024). "KMT2D deficiency was found to impair super-enhancers to confer a glycolytic vulnerability in lung cancer." (PMID 36685901, 2022). "Lysine (K)-specific methyltransferase 2D (KMT2D) deficiency was reported to impair SEs to form glycolytic vulnerability in lung cancer, promote tumorigenesis in mice and upregulate protumorigenic progression, including glycolysis." (PMID 34722892, 2021). "A recent study reported that KMT2D loss contributed to lung cancer growth by enhancing glycolysis." (PMID 40718439, 2025). "Notably, other studies also report that KMT2D loss increases glycolysis in lung cancer, melanoma, and pancreatic cancer." (PMID 39117659, 2024). "Indeed, the pharmacological inhibition of glycolysis selectively impedes the growth of lung cancer and melanoma with KMT2D-inactivating mutations." (PMID 39117659, 2024). "In lung cancer, it has been observed that KMT2D mutations increase the glycolysis of tumor cells." (PMID 36674608, 2023). "Loss of KMT2D reduces the activity of super-enhancers at critical genes, such as the circadian rhythm repressor Per2, resulting in Per2 gene down-regulation, glycolysis and lung cancer tumorigenesis." (PMID 38135679, 2023). "However, in lung cancer, where KMT2D was found to be the most highly inactivated epigenetic modifier, KMT2D-inactivating mutations induce aberrant metabolic reprogramming via increased expression of glycolytic genes." (PMID 35071240, 2021). "Accordingly, pharmacologic inhibition of glycolysis reduces tumorigenicity of human lung cancer cells bearing KMT2D-inactivating mutations, suggesting that KMT2D deficiency may present a therapeutic vulnerability to glycolytic inhibitors." (PMID 35071240, 2021). "Consistently, it is known that KMT2D is among the most highly inactivated epigenetic modifiers in lung cancer." (PMID 35347810, 2022). "KMT2D, CSMD3 and LRP1B were mutated in 15%, 10% and 10% of lung cancer patients, but KMT2D and CSMD3 were mutated in 25% and 12.5% of benign diseases." (PMID 33200540, 2021). "LRP1B, KMT2D, RNF213 and CSMD3 gene mutations were significantly more common in lung cancer than in benign disease (P < 0.05)." (PMID 33200540, 2021). "In the training set, RNF213, KMT2D, CSMD3 and LRP1B were mutated more frequently in early‐stage lung cancer than in benign disease." (PMID 33200540, 2021). "In the training set, the RNF213, KMT2D, CSMD3 and LRP1B genes were mutated more frequently in early‐stage lung cancer (27 cases) than in benign nodules (15 cases) (P < 0.05)." (PMID 33200540, 2021). "Histone methyltransferase KMT2D (also called MLL4) was added to the list and tested in batch 2 only because it has recently been found to be a tumor suppressor and frequently mutated in lung cancer." (PMID 37760474, 2023). "The histone methyltransferase KMT2D is often inactivated in human lung cancer tissues." (PMID 38135679, 2023). "Moreover, KMT2D plays a tumor inhibitory role in melanoma, pancreatic cancer cells, and lung cancer." (PMID 35058979, 2022). "In lung cancer, lysine methyltransferase 2D (KMT2D) is highly expressed and regulates the super enhancers H3K4me1 and H3K27ac of period circadian regulator 2 (PER2; circadian inhibitory factor), affecting the expression of PER2 and its downstream glycolytic genes." (PMID 35004688, 2021). "Notably, KMT2D-deficient lung cancer cells depend on proper glycolytic activities for survival, which is compatible with the notion that loss of TFB1M may be lethal for KMT2D-deficient cells." (PMID 39578878, 2024). "The number of the test genes RNF213, KMT2D, CSMD3 and LRP1B detected in lung cancer samples was five, five, three and two, respectively." (PMID 33200540, 2021).
lung carcinoma (continued). "High expression of RNF213, KMT2D and CSMD3 was observed in lung cancer tissues, and low expression of these genes was observed in benign disease tissues." (PMID 33200540, 2021). "In the training set, the RNF213, LRP1B, KMT2D and CSMD3 genes had statistically significant differences in the sequenced data in lung cancer compared to benign disease." (PMID 33200540, 2021). "The number of missense mutations in the LRP1B, KMT2D, RNF213 and CSMD3 genes was eight (8/27, 29.6%), seven (7/27, 25.9%), seven (7/27, 25.9%) and six (6/27, 22.2%) in the lung cancer group, respectively, and none of the genes were mutated in the benign disease control group." (PMID 33200540, 2021).
bladder cancer (20 papers, 2019 to 2025). "Of these six HMTs, histone lysine N‐methyltransferase 2D (KMT2D) exhibited the highest mutation rate in bladder cancer." (PMID 30984543, 2019). "KMT2D is mutated in different types of cancer, including bladder cancer." (PMID 36674608, 2023). "Additionally, according to our results, significantly increased KMT2D protein expression was detected in patients with a previous history of bladder cancer, which has been reported as a risk factor for bladder recurrence after RNU." (PMID 34834500, 2021). "In summary, our findings indicate that mutations in HMT genes, especially KMT2D mutation, may play a role in the development of bladder cancer." (PMID 30984543, 2019). "In contrast, American patients with bladder cancer tend to harbor mutations that disrupt signaling by GPCR, with CDKN1A, IRS4 and KMT2D identified in the 6-gene set." (PMID 40768543, 2025). "Chromatin regulation genes, including KDM6A, KMT2D, EP300, and ARID1A, show high rates of mutation in bladder cancer, as demonstrated here and in multiple cohort studies." (PMID 41373802, 2025). "Although KMT2D can act as a tumor suppressor in some cancers, such as medulloblastoma or bladder cancer, in esophageal squamous cell carcinoma cells, KMT2D knockout inhibited cell proliferation and migration and reduced epithelial-mesenchymal transition." (PMID 38791111, 2024). "The expression of KMT2D has also been proposed as a prognostic biomarker for bladder cancer in European patients, observing a trend towards greater survival in patients with higher expression of this protein." (PMID 36674608, 2023). "Whole-exome sequencing demonstrated that the mutation frequency of chromatin remodeling genes in bladder cancer was more than 10%, including KDM6A, MLL2 (also known as KMT2D), CREBBP, EP300, and ARID1A." (PMID 35697678, 2022). "To provide further experimental corroboration of their overlapping role in the context of bladder cancer, we used the TCGA bladder cancer cohort to examine the effects of mutations in KDM6A and KMT2D on a number of putative downstream targets of the complex." (PMID 35073341, 2022). "The most frequently mutated genes in the chemo-naïve samples were well-established bladder cancer–associated genes: FGFR3 (70%), KMD6A (47%), PIK3CA (38%), KMT2D (26%), and ARID1A (23%)." (PMID 34934968, 2021). "KMT2D expression was increased in patients with a previous history of bladder cancer (25% vs. 0%, p = 0.02)." (PMID 34834500, 2021). "KMT2D alterations and protein expression were associated with UTUC features such as multifocality, ureteral location, and previous bladder cancer." (PMID 34834500, 2021). "It was reported that miR-217 promoted the proliferation and migration of bladder cancer cells by targeting KMT2D and that miR-217 levels were negatively correlated with KMT2D expression in bladder cancer samples." (PMID 34194626, 2021). "A study of bladder cancer showed that KMT2D was required to maintain tumor suppressor genes and that it impeded the tumorigenicity and invasiveness of bladder cancer cells." (PMID 34194626, 2021). "In bladder cancer, KMT2D functions as a tumor suppressor and supports tumor cell viability, migration, and invasion." (PMID 32239176, 2020). "In summary, bladder cancer’s alterations in histone modification pathways–whether via mutation (KDM6A, ARID1A, KMT2D) or overexpression (EZH2, HDACs) – are a central component of its biology and interact with aging." (PMID 40918525, 2025).
bladder cancer (continued). "However, pathogenic KMT2D alterations and expression were associated with features of clinically aggressive UTUC including multifocality, ureteral location, and previous bladder cancer." (PMID 34834500, 2021). "Through integrative analysis, we identified six HMT genes (PRDM9,ASH1L,SETD3,SETD5,WHSC1L1, and KMT2D) that may play a key role in the development and progression of bladder cancer." (PMID 30984543, 2019). "Since KDM6A connects KMT2D and RB1 mutations we hypothesize that there is a biological pathway that unites the impact of these three mutated genes and is important for the biologic fitness of bladder cancer cells." (PMID 35073341, 2022). "Thus, KMT2D alterations and expression were associated with features of biologically aggressive UTUC including multifocality, ureteral location, a cancer field effect, and previous bladder cancer." (PMID 34834500, 2021). "Beyond KDM6A, other genes involved in epigenetic regulation, including KMT2C (Lysine N-methyltransferase 2C), KMT2D (Lysine N-methyltransferase 2D), and ARID1A (AT-rich interactive domain-containing protein 1A), also display aberrant expression patterns in bladder cancer." (PMID 40600050, 2025). "KMT2D expression and mutational status did not emerge as a prognostic marker for UTUC; however, KMT2D alterations and expression were associated with features of clinically aggressive UTUC such as multifocality, ureteral location, and previous bladder cancer." (PMID 34834500, 2021). "Unlike bladder carcinomas, the most affected genes are FGFR3, HRAS, and KMT2D." (PMID 39064555, 2024).
medulloblastoma (18 papers, 2013 to 2025). A malignant, invasive embryonal neoplasm arising from the cerebellum. "Recurrent epigenetic alterations in SHH-activated medulloblastoma have been described in MLL2/KMT2D and MLL3/KMT2C, two lysine methyltransferases associated with an active chromatin state and the H3K4me2/3 status." (PMID 37568705, 2023). "We have shown that brain-specific loss of Kmt2d alone induces spontaneous medulloblastoma in 34.6% of brains in a genetically engineered mouse model (GEMM)." (PMID 34194626, 2021). "We have shown that loss of the Kmt2d gene in the mouse brain reduced H3K4me1 and H3K4me3 levels in many genes during medulloblastoma genesis." (PMID 34194626, 2021). "Somatic mutations of KMT2D were initially identified in medulloblastoma, thus we sought to first examine its role in human medulloblastoma cancer cell lines." (PMID 24240169, 2013). "In addition, in 16% of cases with childhood medulloblastoma, KMT2D deficiency was found with the majority being protein alternating missense mutations or truncations." (PMID 41035915, 2025). "KMT2D is a tumor suppressor gene with histone lysine methyltransferase activity that is the target of frequent inactivating mutations in several tumor types, including medulloblastoma, diffuse large B cell lymphoma (DLBCL), and follicular lymphoma." (PMID 29950560, 2018). "In addition to its role in medulloblastoma, subsequent studies have found that KMT2D is frequently mutated in other cancers, including 89% of follicular lymphoma and 20%-30% of diffusive large B-cell lymphoma." (PMID 24240169, 2013). "KMT2D is a key regulator of transcriptional enhancer function and plays an important role in maintaining genomic stability, and it is mutated in a large number of different cancers (e.g., diffuse large B cell lymphoma, small cell undifferentiated lung cancer, and medulloblastoma)." (PMID 32164600, 2020). "Our patient had additional mutations at POLE, LYST, KMT2D, and TERT, all of which have been shown to significantly reduce overall survival in medulloblastoma." (PMID 40958970, 2025). "As similar mechanism of action, loss of function of KMT2D inhibits tumor suppressor genes DNMT3A and BCL6, upregulates NOTCH pathway, and induces medulloblastoma in murine models." (PMID 39113693, 2024). "This is also in discrepancy with ours, which showed medulloblastoma-suppressive function of KMT2D using a GEMM." (PMID 34194626, 2021). "We have shown that KMT2D-activated tumor-suppressive super-enhancers interact with the promoters of the DNA methyltransferase gene Dnmt3a and the medulloblastoma suppressor gene Bcl6 and upregulate these genes to suppress medulloblastoma genesis." (PMID 34194626, 2021). "The original medulloblastoma exome sequencing led to the discovery of frequent mutations in the histone lysine methyltransferase gene KMT2D/MLL2 and its homolog KMT2C/MLL3, which were not previously linked to cancer." (PMID 24240169, 2013). "Since there are no known medulloblastoma cell lines with loss-of-function KMT2D mutations (e.g., frameshift mutations), we decided to use a somatic gene knockout strategy." (PMID 24240169, 2013). "In addition, KMT2D activates expression of the tumor suppressor genes Bcl6 and Sirt1, whose proteins repress expression of several oncogenic Notch pathway genes to suppress medulloblastoma." (PMID 34194626, 2021). "This, together with the near absence of homozygous KMT2D inactivating mutations in medulloblastoma, led us to speculate that the role of the KMT2D deficiency in cancer is more complicated than simply driving tumor cell proliferation." (PMID 24240169, 2013). "Further adding to this complexity, the near absence of homozygous KMT2D mutations in medulloblastoma led to the speculation of an oncogenic dependency on KMT2D activity." (PMID 24240169, 2013).
medulloblastoma (continued). "For cases with paired tumor and CSF cfDNA WES (n = 15), a mean of 83 (range 1–160) shared SNVs were observed, including SNVs in classical medulloblastoma genes such as SMO and KMT2D." (PMID 37444642, 2023). "Mechanistically, KMT2D upregulates expression of the tumor suppressor gene Dnmt3a whose protein, DNMT3A, downregulates expression of several oncogenic Ras activators to suppress medulloblastoma." (PMID 34194626, 2021).
diffuse large B-cell lymphoma (16 papers, 2018 to 2025). "Diffuse large B cell lymphomas and follicular lymphomas show recurrent mutations in epigenetic regulators; among these are loss-of-function mutations in KMT2D and gain-of-function mutations in EZH2." (PMID 40504770, 2025). "Mutations in KMT2D gene are highly recurrent and occur early during tumorigenesis in diffuse large B cell lymphoma and follicular lymphoma." (PMID 34232366, 2022). "KMT2D is one of the most frequently mutated genes in diffuse large B-cell lymphoma (DLBCL), with mutations predominantly occurring in the SET domain and PHD domain, which are the primary functional regions of the KMT2D enzyme." (PMID 41372946, 2025). "Histone methyltransferase KMT2D is one of the most frequently mutated genes in diffuse large B-cell lymphoma (DLBCL) and has been identified as an important pathogenic factor and prognostic marker." (PMID 39113693, 2024). "In diffuse large B-cell lymphoma (DLBCL), KMT2D mutations promote the migration of Treg cells into the tumor microenvironment and suppress immune responses through the FBXW7-NOTCH-MYC/TGF-β1 signaling axis, thereby promoting tumor growth." (PMID 41372946, 2025). "Chromatin writers and erasers are frequently mutated in GC-derived lymphomas, mostly in diffuse large B cell lymphomas (DLBCLs) that show prevalent mutations in major epigenetic modifiers such as EZH2, EP300, CREBBP and KMT2D." (PMID 35580618, 2022). "KMT2D and KMT2C (previously known as MLL2 and MLL3, respectively) encode histone H3K4 methyltransferases and are frequently mutated in diffuse large B-cell lymphoma and follicular lymphoma." (PMID 34638403, 2021). "In a study published in 2019, a class of molecular high-grade diffuse large B-cell lymphoma (MHG) was defined, which had significantly higher mutation frequencies than GCB in KMT2D, BCL2, MYC, or DDX3X." (PMID 34925435, 2021). "KMT2D protein level is also regulated by the ubiquitin E3 ligase FBXW7, with loss of KMT2D promoting growth of diffuse large B cell lymphoma cells." (PMID 34109280, 2021). "Mutations in CREBBP, TNFRSF14 and KMT2D predominated in follicular lymphoma, whereas those in BTG2, HTA-A and PIM1 were more frequent in diffuse large B-cell lymphoma." (PMID 33945543, 2021). "A related study also showed that KMT2D was overexpressed in primary gastrointestinal diffuse large B cell lymphoma (PGI-DLBCL) and appeared as a prognostic factor for patients older than 60 years old." (PMID 32164600, 2020). "KMT2D protein levels are reportedly to diminished or absent in many diffuse large B cell lymphoma (DLBCL) cell lines due to KMT2D mutations." (PMID 39025450, 2024). "Our findings were similar to those in primary gastrointestinal diffuse large B cell lymphoma (PGI-DLBCL) and breast and colon cancers, implying that KMT2D may act as a prognostic biomarker for DLBCL patients." (PMID 31403034, 2019).